SPARC (secreted protein acidic and cysteine rich)
Diseases named in the same sentence as SPARC in open-access papers (continued):
Sharing a sentence is not in itself a finding about the gene and the disease.
ischemia (3 papers, 2018 to 2021). A hypoperfusion of the BLOOD through an organ or tissue caused by a PATHOLOGIC CONSTRICTION or obstruction of its BLOOD VESSELS, or an absence of BLOOD CIRCULATION. "A transient early rise in SPARC expression has been linked to both fibroblast migration and effective early extracellular remodeling after ischemia, while SPP1 was found to be essential for effective collagen synthesis preventing LV dilation." (PMID 34895263, 2021). "Currently, the correlation between neurological diseases, such as epilepsy, PD, AD, and ischemia, and SPARC needs to be investigated further." (PMID 33584170, 2020). "Using oxygen and glucose deprivation (OGD) to simulate ischemia in hippocampal slices in vitro, we uncovered a novel role for SPARC in regulating AMPAR and promoting neuroprotection following CNS injury." (PMID 29449802, 2018). "To better dissect the role of SPARC after CNS injury, we used an in vitro model of ischemia, OGD in organotypic hippocampal slices where we could more carefully control the experimental conditions." (PMID 29449802, 2018). "Therefore, regulating the expression of SPARC may be the key to the prevention and control of neurological diseases, such as epilepsy, PD, AD, and ischemia." (PMID 33584170, 2020).
lentivirus infection (3 papers, 2016 to 2020). Virus diseases caused by the Lentivirus genus. "After lentivirus infection and induction by cytokines, RT-PCR and western blot showed that SPARC was overexpressed in M2 compared with M0, which illustrated that the SPARC overexpression M2 model was successfully established." (PMID 32226513, 2020). "Primary GCAFs were obtained and cultured from cancer patients for in vitro study, and a lentivirus infection method was employed to knock down SPARC expression in GCAFs." (PMID 31139014, 2019). "Stable suppression of SPARC protein expression in the Met5A cell line was achieved by introduction of two separate shRNA targets against SPARC by Lentivirus infection." (PMID 27622658, 2016).
metastasis (3 papers, 2004 to 2023). The spread or migration of cancer cells from one part of the body (where they first appeared) to another. "High SPARC gene expression indicated advanced tumor stage (14,58 ± 1,06 vs. 14,3 ± 1,10; p=0,014) and positive lymph node metastasis (14,59 ± 1,05 vs. 14,29 ± 1,09; p=0,00073) in CRC." (PMID 36895491, 2023).
Myocardial fibrosis (3 papers, 2019 to 2022). "SPARC expression is increased in response to cardiac pressure overload, and has been found to be necessary for the development of myocardial fibrosis in this model." (PMID 31547598, 2019). "Macrophage-derived SPARC was found to precede collagen deposition in myocardial fibrosis, which enhanced post-synthetic collagen processing, insoluble collagen content, and contributed to the development of fibrosis in a murine pressure overload model." (PMID 31547598, 2019). "SPARC contributes to myocardial fibrosis in pressure overload." (PMID 35721704, 2022).
oral squamous cell carcinoma (3 papers, 2013 to 2022). "The higher SPARC expression is detected in oral squamous cell carcinoma via immunohistochemical analysis when compared with control tissue." (PMID 28718842, 2017). "Particularly, SPARC proteins were detected in oral squamous cell carcinoma." (PMID 35888170, 2022).
proliferative diabetic retinopathy (3 papers, 2010 to 2022). Advanced retinopathy due to diabetes mellitus characterized by the formation of new vessels in the retina. "SPARC plays an important role in hyalocyte-to-myofibroblast transdifferentiation in proliferative diabetic retinopathy, and deletion of SPARC enhances retinal vaso-obliteration." (PMID 35721704, 2022). "Previous studies found that SPARC plays an important role in hyalocyte-to-myofibroblast transdifferentiation in proliferative diabetic retinopathy." (PMID 35721704, 2022). "In the eye, increased SPARC level has been correlated with cataract, corneal wound repair, and proliferative diabetic retinopathy." (PMID 21042566, 2010).
renal cell carcinoma (3 papers, 2004 to 2023). "Higher SPARC expression was also associated with local tumour invasion in colorectal, breast, bladder and renal cell carcinoma." (PMID 15558074, 2004). "The SPARC promoter contains a Snail binding site, and Snail is involved in TGF-β1-stimulated SPARC expression in renal cell carcinoma cells." (PMID 37158892, 2023). "The binding site for Snail and Slug has been identified in the SPARC promoter, and Snail is required for the TGF-β1-induced SPARC expression in renal cell carcinoma cells." (PMID 37158892, 2023).
scleroderma (3 papers, 2007 to 2023). Scleroderma is a rare autoimmune connective tissue disorder characterized by abnormal hardening of the skin and, sometimes, other organs. "In this hypothesis, it is noteworthy that the 1922 t→g UTR-SNP present on SPARC has been associated with scleroderma, in addition to cancer (our screen)." (PMID 17201911, 2007). "Interestingly, a distinct polymorphism within the SPARC gene, namely 998 c→g, has been associated with susceptibility to and clinical manifestations of scleroderma." (PMID 17201911, 2007). "Therefore, SPARC genetic polymorphisms may represent useful candidate SNPs for screening either susceptibility to cancer (2072 c→t and 2198 g→a) or scleroderma pathogenesis (998 c→g)." (PMID 17201911, 2007). "SPARC, which is also known as osteonectin, has been implicated in the pathogenesis of scleroderma, but not SpA." (PMID 19900269, 2009). "We demonstrated that both inflammation-driving subtypes, CCL19+ and SPARC+COL3A1+/FAP+THY+, are present in scleroderma, possibly promoting inflammation through chemotaxis and enhanced leucocyte infiltration." (PMID 37443817, 2023).
acute lymphoblastic leukemia (2 papers, 2022 to 2024). Leukemia with an acute onset, characterized by the presence of lymphoblasts in the bone marrow and the peripheral blood. "Indeed, bortezomib has been reported to upregulate SPARC expression in the BM stromal cells and this upregulation has an anti-adhesive effect on B cells in acute lymphoblastic leukemia." (PMID 36605435, 2022).
angiosarcoma (2 papers, 2015 to 2016). A malignant tumor arising from the endothelial cells of the blood vessels. "SPARC overexpression was seen in 35.9 % of the cases, with the highest percentages in epithelioid hemangioendothelioma, conventional chondrosarcoma, and angiosarcoma." (PMID 27544129, 2016). "In our study, interestingly, SPARC was overexpressed in angiosarcoma, chondrosarcoma and EHE." (PMID 25906748, 2015). "Overexpression of serum protein acidic and rich in cysteine (SPARC), a biomarker for albumin bound paclitaxel, was seen in 35.9% of the cases, especially in over 60% of epithelioid hemangioendothelioma (EHE) and chondrosarcoma (notably conventional chondrosarcoma), as well as 48.7% of angiosarcomas." (PMID 25906748, 2015). "However, this study did not assess for SPARC status or include patients with angiosarcoma or EHE." (PMID 25906748, 2015).
autosomal dominant polycystic kidney (2 papers, 2011 to 2013). "The SPARC mRNA and protein levels were significantly higher in polycystic kidney tissue from ADPKD patients than in normal kidney tissue." (PMID 23516489, 2013).
cholangiocarcinoma (2 papers, 2023). A carcinoma that arises from the intrahepatic biliary tree (intrahepatic cholangiocarcinoma) or from the junction, or adjacent to the junction, of the right and left hepatic ducts (hilar cholangiocarcinoma). "Some evidence has indicated that SPARC induces M2 polarization of macrophages to promote proliferation, migration, and angiogenesis of cholangiocarcinoma cells, whereas downregulation of SPARC prevents the M2 polarization of macrophages." (PMID 37509139, 2023).
chronic myeloid leukemia (2 papers, 2013 to 2019). "In this study we investigated the variations in SPARC production by peripheral blood cells from chronic myeloid leukemia (CML) patients at diagnosis and after treatment and we identified the subpopulation of cells that are the prevalent source of SPARC." (PMID 23383963, 2013).
ductal carcinoma in situ (2 papers, 2016 to 2019). "SPARC expression has been associated with invasiveness phenotype in patients with ductal carcinoma in situ, as well as with poor survival in patients with TNBC." (PMID 31488082, 2019).
endometriosis (2 papers, 2018 to 2019). The growth of functional endometrial tissue in anatomic sites outside the uterine body. "SPARC has been a gene of interest in multiple endometrial disease pathologies including endometriosis where it has been reported as deregulated in endometriotic lesions in women with endometriosis." (PMID 30061686, 2018).
fibroids (2 papers, 2019 to 2022). "Although the expression of CTB-113P19.1 was lower in leiomyomas, its overlapped transcript SPARC was significantly higher." (PMID 35641855, 2022). "However, the expression of CTB-113P19.1 was decreased in leiomyomas, while its overlapping protein coding gene, SPARC, was upregulated." (PMID 35641855, 2022). "Our findings implicate SE-lncRNAs in leiomyoma tumorigenesis and progression through the regulation of potential downstream target genes which are in close proximity to their transcription sites (e.g., SOCS2, CBX4, HOXA11, PRL, SPARC, and EGFLAM)." (PMID 35641855, 2022). "Because SPARC regulates cell–matrix interactions and also regulates the activity of many growth factors, such as fibroblast growth factor (FGF)-2, vascular endothelial growth factor (VEGF), and platelet-derived growth factor (PDGF), it could play a significant role in leiomyoma pathogenesis." (PMID 35641855, 2022).
head and neck squamous cell carcinoma (2 papers, 2017 to 2021). A squamous cell carcinoma that arises from any of the following anatomic sites: lip and oral cavity, nasal cavity, paranasal sinuses, pharynx, larynx, and salivary glands. "miR-203 controls head and neck squamous cell carcinoma metastasis by targeting a network of prometastatic proteins, including LASP1, SPARC, and NUAK1." (PMID 29262657, 2017).
hemorrhagic stroke (2 papers, 2021 to 2025). A stroke caused by a bleed on the brain. "Our study revealed that six druggable genes were associated with hemorrhagic stroke, and the inhibition of TNFSF12, SLC22A4, and SPARC had preventive effects against hemorrhagic strokes." (PMID 38977622, 2025). "However, the effects of SPARC in hemorrhagic stroke have been poorly understood." (PMID 34804372, 2021). "We can conclude that TNFSF12, SLC22A4, and SPARC may induce IA, SAH, and ICH and that blocking these targets may have a protective effect against hemorrhagic stroke." (PMID 38977622, 2025). "Our study provides the first comprehensive exploration of targets involved in SAH and ICH using eQTL data to provide genetic support for hemorrhagic stroke drug development and is the first to report that TNFSF12, SLC22A4, and SPARC have preventive effects on IA, SAH, and ICH." (PMID 38977622, 2025).
idiopathic osteoporosis (2 papers, 2010 to 2023). "Moreover, SPARC 3′-UTR polymorphisms had been associated with bone density in Caucasian men with idiopathic osteoporosis." (PMID 21042566, 2010).
Impaired glucose tolerance (2 papers, 2020 to 2022). An abnormal resistance to glucose, i.e., a reduction in the ability to maintain glucose levels in the blood stream within normal limits following oral or intravenous administration of glucose. "SPARC-deficient mice have been shown to exhibit impaired glucose tolerance and insulin secretion, but the underlying mechanism remains unknown." (PMID 33067534, 2020).
Infertility (2 papers, 2021 to 2023). "In C. elegens, SPARC is expressed in the body wall, sex muscle and gonad whereupon downregulation results in larval lethality, transparency in surviving progenies, and infertility or reduced fecundity." (PMID 34041233, 2021). "By illustrating the potential physiological and pathological roles of TGF-β1 in the regulation of SPARC in hGL cells, our results may serve to improve current strategies used to treat clinical infertility and OHSS." (PMID 37158892, 2023).
invasive carcinoma (2 papers, 2015 to 2019). A carcinoma that is not confined to the epithelium, and has spread to the surrounding stroma. "For Patient 2, the expression of SPARC occurred both in infiltrated-invasive carcinoma and in the infiltrating-lobular component." (PMID 26703564, 2015). "Some of the most significant differential mRNA expressions were found for COL1A1, SPARC, and LGALS1 that were stronger expressed in invasive carcinoma compared to high‐grade dysplasia, and the opposite was shown for S100A7, which was stronger expressed in high‐grade dysplasia." (PMID 31454186, 2019). "Neither type I collagen nor SPARC were found to be expressed at all in dysplastic epithelium or in invasive carcinomas." (PMID 31454186, 2019).
invasive ductal carcinoma (2 papers, 2016 to 2022). "SPARC protein expression was significantly associated with interstitial remodeling, the loss of CD34, and α-SMA expression in invasive ductal carcinoma and interfered with TGF-β1 signaling, which allowed it to play a role in tumor progression." (PMID 35211625, 2022).
keratoconus (2 papers, 2011 to 2023). A degenerative, structural disorder of the eye, characterized by a cone-shaped protrusion of the cornea. "Although OMIM links the gene to autosomal recessive osteogenesis imperfecta, missense variants in SPARC have been detected in patients with keratoconus, so the involvement of the gene in the pathology is possible." (PMID 37895187, 2023). "In this study, we report the mutational analysis results for VSX1, LOX, SPARC, TIMP3, and SOD1, performed in a large cohort of Italian subjects affected by sporadic and familial keratoconus." (PMID 21976959, 2011). "LOX and SPARC are localized on chromosome 5q23.2 and 5q31.3-q32, respectively, in regions that show a suggestive linkage in familial keratoconus and thus are both indicated as possible candidate genes for keratoconus." (PMID 21976959, 2011). "Mutational analysis of VSX1, SPARC, and SOD1 in 302 subjects affected by keratoconus." (PMID 21976959, 2011). "A possible role of SPARC in keratoconus has been hypothesized because of its function and position." (PMID 21976959, 2011). "In addition, the proximal location of SPARC to the LOX gene, residing on chromosomes 5q31.3-q32 and 5q23.2, respectively, could also suggest its contribution to keratoconus." (PMID 37895187, 2023).
liver disease (2 papers, 2013 to 2022). "By mean of a genetic approach we herein provide evidence from different in vivo liver disease models suggesting a profibrogenic role for SPARC." (PMID 23408952, 2013).
lung disease (2 papers, 2020 to 2023). "Our data strongly support a function for SPARC in human IPF lung tissue and fibrosing lung disease." (PMID 37758700, 2023).
multiple myeloma (2 papers, 2010 to 2022). "In addition, regulation of myeloma-promoting genes by SPARC-secreting FDCs was assessed in in vitro GC reactions (GCRs)." (PMID 36605435, 2022).
myelodysplastic syndrome (2 papers, 2014 to 2022). A clonal hematopoietic disorder characterized by dysplasia and ineffective hematopoiesis in one or more of the hematopoietic cell lines. "Similarly, lenalidomide (Revlimid) has been shown to induce >2-fold increase in SPARC expression in cultured cells isolated from patients with myelodysplastic syndromes, which may explain the anti-proliferative, anti-adhesion, and anti-angiogenic properties of this drug." (PMID 36605435, 2022).
ocular hypertension (2 papers, 2020 to 2023). Abnormally high intraocular pressure. "A key regulator of the TGF-β2-mediated ocular hypertension node is SPARC." (PMID 37577749, 2023).
oesophageal cancer (2 papers, 2004 to 2011). "High SPARC expression has been associated with enhanced tumour growth, metastasis and poor disease prognosis in various malignancies including melanoma, breast and oesophageal cancers." (PMID 21818290, 2011).
parasite infection (2 papers, 2021 to 2022). "In contrast, a significant increase in SPARC mRNA occurs in the frontal cortex, an area of the brain associated with parasite infection and inflammation, beginning at day 7 and peaking at day 14 post-infection." (PMID 33633185, 2021). "Following infection with T. gondii, we observed an upregulation of SPARC in the frontal cortex of the brain, an area associated with parasite infection 76,77." (PMID 33633185, 2021). "Genes encoding CLU, SPARC and PLAU, were also higher more than 1fold, log2 in Holstein cells and modulated by parasite infection." (PMID 35061738, 2022). "Together, these data demonstrate SPARC upregulation in the CNS as a result of parasite infection." (PMID 33633185, 2021).
prostate adenocarcinoma (2 papers, 2014 to 2024). "When SPARC knockout mice were crossed with TRAMP mice (a model of prostate adenocarcinoma), the genetic presence of SPARC resulted in a lower degree of tumor cell proliferation." (PMID 38928185, 2024).
pulmonary hypertension (2 papers, 2023 to 2025). Increased pressure within the pulmonary circulation due to lung or heart disorder. "In previous studies in human subjects and mice with pulmonary hypertension, SPARC was shown to be overexpressed in lungs, and SPARC suppression using adenovirus vector attenuated cardiac and hemodynamic disorders." (PMID 40362650, 2025). "Studies on a mouse model of pulmonary hypertension under hypoxia conditions showed that TGF-β1 or hypoxia-inducing factor 2α (HIF2α) signaling pathway induces the expression of SPARC in human pulmonary artery smooth muscle cells (PASMCs)." (PMID 38076208, 2023).
rectal cancer (2 papers, 2023). A primary or metastatic malignant neoplasm that affects the rectum. "In rectal cancer, SPARC mRNA expression more than cut-off was associated with poor OS (p=0,0061), poor DFS (p=0,0371) and poor PFS (p=0,0120)." (PMID 36895491, 2023). "High protein expression of SPARC and SPP1 was associated with shorter recurrence-free survival (RFS) and PFS, respectively, in patients with rectal cancer (respectively)." (PMID 36895491, 2023). "Using digital quantification, we performed IHC analysis of S100A4, SPP1 and SPARC in human colon and rectal cancer tissue." (PMID 36895491, 2023). "Rectal cancer patients with high SPARC expression have poor prognosis." (PMID 37577749, 2023). "We for the first time performed complex analysis of S100A4, SPP1 and SPARC mRNA levels in terms of survival rates in common CRC groups and in patients with colon and rectal cancer separately." (PMID 36895491, 2023). "SPARC mRNA level was independent prognostic factors for survival in colon but not in rectal cancer." (PMID 36895491, 2023). "Thus, we concluded that SPARC mRNA expression could serve as an independent prognostic factor for DFS and PFS in colon but not rectal cancer." (PMID 36895491, 2023).
renal fibrosis (2 papers, 2021 to 2026). A final common manifestation of a wide variety of chronic kidney diseases characterized by glomerulosclerosis and tubulointerstitial fibrosis. "The SPARC-CBP-DOT1L axis thus defines a previously unrecognized epigenetic pathway driving renal fibrosis." (PMID 42212322, 2026). "Overexpression of SPARC has been shown to colocalize with collagen, and participate in extracellular matrix deposition and renal fibrosis." (PMID 33936064, 2021).